CDH3 (cadherin 3)
Diseases named in the same sentence as CDH3 in open-access papers (continued):
Sharing a sentence is not in itself a finding about the gene and the disease.
colorectal cancer (18 papers, 2011 to 2025). A primary or metastatic malignant neoplasm that affects the colon or rectum. "This indicates the strong predictive power of high CDH3 expression in predicting distant metastasis in colorectal cancer." (PMID 39247592, 2024). "The research by Sharma G emphasizes the crucial role of CDH3 in regulating cell proliferation, migration, and apoptosis in colorectal cancer." (PMID 39247592, 2024). "Specifically, CDH3 functions in the regulation of cell adhesion and is likely involved in the progression and metastasis of colorectal cancer." (PMID 39146279, 2024). "CDH3 is highly expressed in cancer tissues such as colorectal cancer, thyroid cancer, and pancreatic cancer, but the study of CDH3 in gastric cancer is not completely clear." (PMID 34485109, 2021). "Our results suggest that MIR133A regulates CDH3 in human colorectal cancer and may be helpful for CRC." (PMID 37151391, 2023). "Of note, CDH3 expression levels in colorectal cancer (CRC) remain less well characterized." (PMID 29142905, 2017). "Aberrant expression of the classical cell–cell adhesion molecule P-cadherin (P-cad; encoded by the CDH3 gene, referred to here as P-cad) has been associated with aggressive tumor behavior in breast, gastric, prostate, pancreatic, bladder and colorectal carcinomas, among others." (PMID 36808468, 2023).
pancreatic cancer (18 papers, 2008 to 2025). "Indeed, cadherin-2 and cadherin-3 expressions, which are associated with malignant clinicopathological characteristics, respectively in hepatocellular carcinoma and pancreatic cancer are downregulated." (PMID 31803360, 2019). "Overexpression of CDH3 has been reported to promote the movement of pancreatic cancer cells by interacting with P120ctn and activating Rho family GTPases." (PMID 34956309, 2021). "Taking into consideration that experiments in mice suggest a role of AdipoR2 in pancreatic islet cell maintenance, there might be some connection between Cdh3 and Adipoq functions in the process of developing pancreatic cancer." (PMID 22291890, 2012). "We have reported that CDH3/P-cadherin is another TAA that is overexpressed in pancreatic cancer; however, it has been often observed that using a single TAA as a target of anticancer immunotherapy does not yield satisfactory therapeutic outcomes in animal models." (PMID 21179034, 2011). "By integrated analysis of our data and publicly available bioinformatics resources, we found that a combination panel consisting of CDH3, PLAU, and LFNG might improve the prognosis of overall pancreatic cancer survival." (PMID 27869176, 2016). "Cdh3 is a P-cadherin gene which is overexpressed in the majority of pancreatic cancer, but not in healthy cells." (PMID 22291890, 2012). "Besides CRC, CDH3 was also overexpressed in the majority of pancreatic cancer and gastric cancer, but not in their noncancerous counterparts or in normal tissues." (PMID 22496748, 2012).
lung carcinoma (17 papers, 2005 to 2025). "CDH3 has also been reported to be associated with prognosis in patients with colorectal adenocarcinoma and lung cancer." (PMID 34956309, 2021). "We identified at least five proteins of interest (NKX2-1, CAV1, YBX1, FN1 and CDH3) with two different machine learning models that may be associated with lung cancer patient survival." (PMID 33086649, 2020). "Analysis of The Cancer Genome Atlas (TCGA) database reveals that CDH3 is widely and highly expressed in various cancers, including lung cancer." (PMID 40227353, 2025). "Next, the GSEA analysis was conducted using a gene set comprising CDH1, CDH2, and CDH3 to investigate their collective role in lung cancer." (PMID 40860670, 2025). "For example, increased expression of the CDH3 gene promotes proliferation, migration, invasion, and chemoresistance in oral squamous cell carcinoma, lung cancer, and thyroid cancer." (PMID 39682235, 2024). "Furthermore, our study investigated the relationship between IPF-ARGs and lung cancer, identifying CDH3 as an oncogenic gene and recognizing EDNRB, MAOA, and PLA2G1B as tumor suppressor genes." (PMID 40589973, 2025). "However, the expression and regulatory mechanism of CDH3 under oxidative stress in lung cancer remain poorly understood." (PMID 40227353, 2025). "Interestingly, in very recent studies, CDH3 (also known as Cadherin-3 or Placental-Cadherin), have been shown to be served as an accurate survival predictor in lung cancer and poor prognosis biomarker among patients with tongue squamous cell carcinoma, indicating its importance in other cancers." (PMID 35907803, 2022). "Similarly, in lung cancer, radioresistance-related signatures also predict patient outcomes and immune status, identifying TOP2A, CDH3, ASPM, CENPF, SLC2A1, and PRC1 as potential detection biomarkers for early lung cancer." (PMID 41041339, 2025).
breast tumors (16 papers, 2012 to 2025). "Basal HNSCC and basal-like breast tumors both overexpress Bullous Pemphigoid Antigen 1, P-Cadherin (CDH3), Laminin γ 2 (LAMC2), and Collagen XVII-α (COL17A1)." (PMID 40867349, 2025). "CDH3 is overexpressed in highly malignant breast tumors, and is an independent prognostic factor in lymph node malignancy." (PMID 31105876, 2019). "P-cadherin, a classical cadherin encoded by the CDH3 gene, has been explored by our group for several years and has been also extensively associated with breast tumour aggressiveness." (PMID 23405208, 2013). "Gorski and collaborators also demonstrated that BRCA1 and c-Myc form a repressor complex on CDH3 promoter and on other promoters of specific basal genes, representing a potential mechanism to explain the overexpression of key basal markers in BRCA1-deficient breast tumours." (PMID 23405208, 2013). "For example, CDH3 was significantly up-regulated in the stromals of both breast and prostate tumors, however EGFR was only significantly down-regulated in the stromal of breast tumor." (PMID 25826086, 2015).
colon carcinoma (14 papers, 2011 to 2024). "This is also shown for colon cancer cells where knockdown of CDH3 also resulted in reduced β-catenin expression and upregulated CDH1, called the cadherin switch." (PMID 31105876, 2019). "Thus, it is possible that the expression of CDH3 is also increased in colon cancer." (PMID 21575255, 2011).
gastric cancer (13 papers, 2010 to 2024). A primary or metastatic malignant neoplasm involving the stomach. "CDH3, a gene predominantly overexpressed in gastric cancer, is associated with cancer invasion and metastasis." (PMID 39336798, 2024). "Through the cubic spline interpolation algorithm, we found that the high-risk warning indicator of gastric cancer was 8<CDH3<15 and 10<expression of LEF1<16." (PMID 34485109, 2021). "The high-risk warning indicator of gastric cancer contained 8<CDH3<15 and 10<expression of LEF1<16." (PMID 34485109, 2021). "In our study, LEF1 was found to predict gastric cancer jointly with CDH3 and MMP7, which may be used as a diagnostic marker for gastric cancer in the future." (PMID 34485109, 2021). "Thus CDH3 was regarded as a novel tumor-associated antigen useful for immunotherapy and early diagnosis of gastric cancer and CRC." (PMID 22496748, 2012). "Our data provide evidence that loss of E-cadherin is able to compromise the normal interactions between the CDH1 to CDH3 gene sequences, allowing the expression of P-cadherin in gastric cancers." (PMID 37372088, 2023). "We induced this switch by depleting CDH1 in gastric cancer cells, and, as they started to produce CDH3, this rescued cell-adhesion." (PMID 37372088, 2023). "Our research found that CDH3 is highly expressed in gastric cancer tissues, and it is included in the neural network model for prediction." (PMID 34485109, 2021). "Herein, we aimed to characterize a potential 3D chromatin architecture re-wiring process, occurring at the CDH3–CDH1 loci, that may explain the CDH1/E-cadherin to CDH3/P-cadherin switch observed in gastric cancer." (PMID 37372088, 2023). "First, we demonstrated that 75% of the gastric cancers analysed overexpressed CDH3." (PMID 37372088, 2023). "Given the abundance of gastric cancers bearing simultaneous loss of CDH1 expression and CDH3 upregulation, we tested whether depleting CDH1 would trigger CDH3 upregulation." (PMID 37372088, 2023). "To understand the frequency of and explore potential mechanisms which underly E- to P-cadherin switching in gastric cancer, we started by analysing RNA-seq data from 43 gastric cancers to evaluate CDH1 and CDH3 mRNA expression." (PMID 37372088, 2023). "We unveiled a mechanism explaining the E- to P-cadherin switch (CDH1 to CDH3 switch), which we found to occur in many gastric cancers." (PMID 37372088, 2023). "A western blotting experiment was carried out, and the results showed that the relative expression levels of MMP7, CDH3, and LEF1 in gastric cancer tissues were increased compared with the control group." (PMID 34485109, 2021). "Pearson’s correlation coefficient displayed that gastric cancer outcome was significantly correlated with the expression of MMP7, CDH3, and LEF1 (p<0.05)." (PMID 34485109, 2021). "Gastric cancer remained related to MMP7, CDH3, and LEF1 (p<0.05) in the univariate linear regression model." (PMID 34485109, 2021). "Immunohistochemical results showed that the expression level of MMP7, CDH3, and LEF1 in gastric cancer tissues was higher than in the control group." (PMID 34485109, 2021). "This study showed that MMP7, CDH3, and LEF1 are highly expressed in gastric cancer tissues." (PMID 34485109, 2021). "This study shows that MMP7, CDH3, and LEF1 are highly expressed in gastric cancer tissues." (PMID 34485109, 2021). "The result demonstrated that MMP7, CDH3, and LEF1 might be identified as biomarkers for gastric cancer." (PMID 34485109, 2021). "While these data provide a rationale for E- to P-cadherin switch in gastric cancer, they do not inform whether the eQTL promotes CDH3 expression." (PMID 37372088, 2023). "CDH3, LEF1, and MMP7 can be used as candidate biomarkers to construct a neural network model from hub genes, which may be helpful for the early diagnosis of gastric cancer." (PMID 34485109, 2021).
oral squamous cell carcinoma (9 papers, 2005 to 2025). "In OSCC, CDH3 is up-regulated and associated with a poor prognosis, promoting migration, invasion, and chemo-resistance in oral squamous cell carcinoma." (PMID 39869563, 2025).
bladder cancer (8 papers, 2012 to 2023). "Comparable results have been described for bladder cancer where the loss of the CDH3 protein signal was associated with muscle invasiveness, high grade (G3) tumors, nodal extension, and poor clinical outcomes and prognoses with respect to long-term and overall survival." (PMID 38003666, 2023). "Additionally, we examined the effects of siRNA-induced suppression of CDH1 CDH3 expression in a bladder cancer cell line model 5637, which, unlike the RCC cell line used in our study, shows substantial endogenous CDH3 expression." (PMID 38003666, 2023).
prostate carcinoma (8 papers, 2010 to 2025). A carcinoma that arises from epithelial cells of the prostate gland. "Also, there were examples of EV-associated messenger RNA and microRNA, e.g. CDH3, or miR-196a-5p, being consistently downregulated in prostate cancer, and examples of other types of small noncoding RNA such as snoRNA and tRNA detectable in EVs." (PMID 31162490, 2018). "In other urological malignancies, including bladder and prostate cancer, CDH3 has been shown to be negatively regulated at the genomic and transcriptional levels and associated with poor clinical outcomes." (PMID 38003666, 2023). "Our findings of CDH1 and CDH3 promoter hypermethylation in NSCLC tumors, with relatively stable methylation for CDH2, are consistent with studies in gastric and prostate cancers." (PMID 40860670, 2025).
ectodermal dysplasia (7 papers, 2015 to 2026). "Though a CDH3 homozygous truncating mutation has been previously implicated in ectodermal dysplasia, ectrodactyly, and macular dystrophy syndrome, these patients were not reported to exhibit orofacial clefting." (PMID 41231213, 2026). "CDH3/P-cadherin mutations have been associated with abnormal development syndromes, including hypotrichosis with juvenile macular dystrophy (HJMD) and ectodermal dysplasia, ectrodactyly and macular dystrophy (EEM syndrome)." (PMID 34680444, 2021). "Importantly, mutations of human CDH3 (the gene encoding P-cadherin) cause two rare autosomal recessive disorders: Hypotrichosis with Juvenile Macular Dystrophy (HJMD) and Ectodermal Dysplasia, Ectrodactyly, and Macular Dystrophy (EEM syndrome)." (PMID 29338041, 2018). "CDH3 on 16q22.1 is responsible for two rare autosomal recessive disorders with hypotrichosis and progressive macular dystrophy: Hypotrichosis with Juvenile Macular Dystrophy and Ectodermal Dysplasia, Ectrodactyly and Macular Dystrophy." (PMID 28061825, 2017). "Several CDH3/P-cadherin germline mutations have been shown to cause P-cadherin functional inactivation, leading to developmental defects associated with hypotrichosis with juvenile macular dystrophy (HJMD) and ectodermal dysplasia, ectrodactyly, and macular dystrophy (EEM syndrome)." (PMID 26438065, 2015).
hepatocellular carcinoma (7 papers, 2016 to 2022). A malignant tumor that arises from hepatocytes. "It has been suggested that CDH3 is down-regulated and exerts tumor suppressive functions in hepatocellular carcinoma and a prior study reported changes of CDH3 in PCa." (PMID 26771841, 2016). "As a result, combinations of CDH3, LFNG, and PLAU were significantly associated with overall survival (log-rank test p-value: 2.376 × 10−5) compared to other protein combinations and cancers (e.g. hepatocellular carcinoma, colorectal adenocarcinoma, and lung adenocarcinoma)." (PMID 27869176, 2016).
invasive breast carcinoma (6 papers, 2012 to 2020). A carcinoma that infiltrates the breast parenchyma. "Thus, based on the hypothesis that C/EBPβ directly activates the CDH3 gene promoter, a double immunostaining was performed in all invasive breast carcinomas that previously showed strong positivity for both proteins." (PMID 23405208, 2013).
non-small cell lung carcinoma (6 papers, 2015 to 2025). A group of at least three distinct histological types of lung cancer, including non-small cell squamous cell carcinoma, adenocarcinoma, and large cell carcinoma. "High CDH3 expression is associated with tumor progression in invasive epithelial tumors and non-small-cell lung cancer." (PMID 36685820, 2022).
Macular dystrophy (5 papers, 2015 to 2026). Macular dystrophy is a nonspecific term for retinal degeneration, generally confined to the macula, usually presumed of genetic origin. "Mutations in four cadherin, namely CDHR1, CDH23, PCDH15, CDH3, the latter being the dominant RPE cadherin, have been identified as causes of inherited retinal degeneration, including cone-rod dystrophy, macular dystrophy and Retinitis Pigmentosa." (PMID 36645183, 2023).
thyroid cancer (5 papers, 2021 to 2024). "Similarly, in a thyroid cancer cell line, the downregulation of CDH3 inhibited cell proliferation, migration, and invasion." (PMID 34530820, 2021).
adenoma (4 papers, 2010 to 2017). A neoplasm arising from the epithelium. "The genes CDH3, ECM1, IGFBP2, and MET, which are associated with cell adhesion, the extracellular matrix, and cancer cell invasion/metastasis, are also observed frequently increased in these two adenoma samples." (PMID 27100181, 2016).
colon adenocarcinoma (4 papers, 2010 to 2024). "A previous study reported that CDH3 is upregulated in colon adenocarcinoma, and patients with high CDH3 have a good prognosis for cancer 8,9." (PMID 37151391, 2023). "CDH3 mRNA was upregulated in colon adenocarcinoma tissue compared to normal colon tissue." (PMID 39146279, 2024). "A study of colon adenocarcinoma using TCGA database showed that cadherin 3 (CDH3) was significantly upregulated in colon adenocarcinoma compared with para-tumor tissues, but the survival analysis showed that higher CDH3 expression was associated with a favorable survival rate." (PMID 32432037, 2020).
colorectal tumor (4 papers, 2016 to 2025). "CDH3 (P-cadherin), a calcium-dependent adhesion molecule, is frequently overexpressed in colorectal tumors." (PMID 40722723, 2025).
esophageal cancer (4 papers, 2019 to 2024). A primary or metastatic malignant neoplasm involving the esophagus. "Long noncoding RNA ADAMTS9-AS2 is downregulated in esophageal cancer, and research has shown that ADAMTS9-AS2 can repress the proliferation, invasion, and migration of esophageal cancer by mediating CDH3 promoter methylation." (PMID 39044262, 2024). "In short, SFE inactivated the Wnt pathway by downregulating SCD and CDH3 expression to suppress esophageal cancer cell metastasis." (PMID 32873775, 2020). "In this study, we showed that SFE could inactivate it through inhibiting SCD and CDH3 expression to regulate esophageal cancer cell metastasis." (PMID 32873775, 2020). "Proving SFE could decrease SCD and CDH3 expression in vitro and in vivo, we identified SCD and CDH3 were the targets of SFE in esophageal cancer cells." (PMID 32873775, 2020). "Then we verified SFE could inactivate the Wnt pathway while SCD and CDH3 overexpression reactivated it in esophageal cancer cells." (PMID 32873775, 2020). "Next, we tested whether SCD and CDH3 played an important role in esophageal cancer cells." (PMID 32873775, 2020). "Microarray results showed the influence of SFE on esophageal cancer cells was related with stearoyl-CoA desaturase (SCD), cadherin 3 (CDH3), mitogen-activated protein kinase kinase 3 (MAP2K3) and growth arrest and DNA damage inducible beta (GADD45B)." (PMID 32873775, 2020). "We had proven that SFE could significantly inhibit esophageal cancer cell progression, and SCD and CDH3 were involved in SFE inhibition of cell metastasis, yet the mechanism by which SFE inhibited cell proliferation was still unclear." (PMID 32873775, 2020).